SLC45A3 (solute carrier family 45 member 3)
Description:
Proton-associated sucrose transporter. May be able to transport also glucose and fructose.
Synonyms: PCANAP6; PRST; IPCA-6; prostein; IPCA-2; IPCA-8; IPCA6; PCANAP2; PCANAP8
Tractability: Antibody: its Gene Ontology location is reachable by antibodies, with high confidence; UniProt predicts a signal peptide or a membrane-spanning region.
Gene: Protein-coding gene on chromosome 1 (205,657,851 to 205,680,990, reverse strand). Ensembl gene ENSG00000158715.
Subcellular location: Membrane
Subcellular location (Human Protein Atlas): Vesicles; Nucleoplasm
Pathways (Reactome):
Transport of small molecules: Cellular hexose transport
Gene Ontology:
Molecular function: sucrose:proton symporter activity; sugar transmembrane transporter activity; transmembrane transporter activity
Biological process: hexose transmembrane transport; positive regulation of fatty acid biosynthetic process; positive regulation of glucose metabolic process; regulation of oligodendrocyte differentiation; sucrose transport; transmembrane transport
Cellular component: plasma membrane; membrane
Genetic constraint (gnomAD): Loss-of-function variants: 17 observed, 35.05 expected, observed/expected ratio (o/e) 0.49, 90% interval 0.33 to 0.73. The upper end of that interval is the gene's LOEUF score, 0.73, which puts it in group 2 of 6, group 1 being the genes least tolerant of losing a copy. Missense variants: 597 observed, 753.08 expected, observed/expected ratio (o/e) 0.79, 90% interval 0.74 to 0.85. Synonymous variants: 288 observed, 343.42 expected, observed/expected ratio (o/e) 0.84, 90% interval 0.76 to 0.93.
Homologues: Orthologues: chimpanzee SLC45A3 (99% identical), macaque SLC45A3 (98% identical), pig SLC45A3 (93% identical), dog SLC45A3 (92% identical), rat Slc45a3 (92% identical), mouse Slc45a3 (91% identical), guinea pig SLC45A3 (86% identical), rabbit SLC45A3 (80% identical), tropical clawed frog slc45a3 (54% identical), zebrafish slc45a3 (48% identical), Drosophila melanogaster lovit (25% identical), Drosophila melanogaster Slc45-1 (24% identical). Paralogues in human: SLC45A4 (25% identical), SLC45A1 (24% identical), SLC45A2 (22% identical).
Diseases named in the same sentence as SLC45A3 in open-access papers:
SLC45A3 is named in the same sentence as 17 diseases in open-access papers, as found by Europe PMC text mining. Sharing a sentence is not in itself a finding about the gene and the disease. The quoted sentences say what the papers report.
prostate carcinoma (34 papers, 2011 to 2025). A carcinoma that arises from epithelial cells of the prostate gland. "Gene rearrangements in SLC45A3 were concurrent with ERG rearrangements in a prostate cancer cohort, with SLC45A3-ERG gene re-arrangement associated with loss of SLC45A3 protein expression and an unfavorable clinical course in prostate cancers." (PMID 32584883, 2020). "SLC45A3, encoding the solute carrier family 45, member 3 protein, also known as prostate cancer-associated protein 6, has been related to prostate-specific antigen serum concentrations and prostate cancer." (PMID 33045005, 2020). "A study reported that the rearrangement of ERG with SLC45A3 and the loss of SLC45A3 expression were one of the aggressive pathways of prostate cancer progression." (PMID 31228945, 2019). "These include associations between 1-monoolein and GATA2, a key regulator of hematopoiesis, or SLC45A3, a known diagnostic marker for prostate cancer." (PMID 26086077, 2015). "For example, TMPRSS2-ERG and SLC45A3-BRAF fusions in prostate cancer similarly amplify oncogene expression via highly active promoters." (PMID 41422314, 2025). "In contrast, we observed minimal differences in the levels of prostate and prostate cancer-associated proteins, including KLKB1, KLK2, KLK3, ACP3, and SLC45A3, which are markers of conventional adenocarcinoma of the prostate." (PMID 39910169, 2025). "In this cohort, we identify mirrored-subclonal copy-number aberrations in all 10 of these cases, including parallel amplification of ELK4 and SLC45A3 which comprise a chimeric transcript known to be related to cell proliferation in prostate cancer." (PMID 38773520, 2024). "Previous research on SLC45A3 mainly focused on prostate cancer, revealing that its expression was heterogeneous and was highly induced in prostate cancers of certain subset." (PMID 36913120, 2024). "In prostate cancer samples, SLC45A3 was also found to be a 5′ fusion partner, and exon 8 of ETV5 was fused to exon 1 of SLC45A3, resulting in ETV5 gene rearrangements." (PMID 36872348, 2023). "Researchers discovered rare 5′ fusions of ETV5 with TMPRSS2 and solute carrier family 45 member 3 (SLC45A3) in prostate cancer." (PMID 36872348, 2023). "SLC45A3:ERG (S:E) fusion is found in approximately 6% of ERG fusion prostate cancer, and concurrent TMPRSS2 and SLC45A3 fusions to ERG are found in 11% of ERG fusion-positive cancer." (PMID 36579559, 2022). "So far, the most studied one in prostate cancer is the one where SLC45A3 is involved in the generation of a chimeric transcript with ELK4." (PMID 33634124, 2021). "A few fusion partners, such as SLC45A3 identified in patients with prostate cancer, can drive overexpression of FGFR2 through promoter exchange." (PMID 34732230, 2021). "The expression of SLC45A3 was reported to be lower in prostate cancer tissue compared to benign tissue, however, androgen induced expression of SLC45A3 in prostate cancer cells." (PMID 32584883, 2020). "TMPRSS2-ERG is the frequent ERG gene rearrangement observed in prostate cancer and SLC45A3 is the second most common ERG partner in prostate cancer and in most of patients SLC45A3-ERG rearrangements co-occur with TMPRSS2-ERG rearrangements." (PMID 31366128, 2019). "Conversely, some lineage-specific genes are seen to serve as 5′ partners across multiple different 3′ genes; for example, TMPRSS2 and SLC45A3 in prostate cancer have been observed as 5′ partners of ERG, ETV1, ETV4, ETV5, BRAF, and ELK4." (PMID 26684754, 2015). "The SLC45A3 gene locus is frequently involved in genomic alterations in prostate cancer." (PMID 36337169, 2022). "SLC45A3 overexpression was reported in aggressive prostate cancer progression." (PMID 32678044, 2020).
prostate carcinoma (continued). "As an example, in prostate cancer rearrangements occurred between untranslated exon 1 of SLC45A3 (a prostate-specific androgen responsive gene) and exon 8 of BRAF (GenBank GU149303) or between exon 13 of ESRP1 (an epithelial splicing regulatory protein) and exon 6 of RAF1 (GenBank GU149302)." (PMID 25473895, 2015). "Immunohistochemical information from the HPA database showed that higher staining of GSTM4, PLP1, and PTGS2 was found in normal prostate tissue, while higher staining of SLC27A2, SLC45A3, APOE, and ABCC4 was observed in prostate cancer tissue." (PMID 40861808, 2025). "A well-characterized example is the cis-SAGe between SLC45A3 and the ETS transcription factor ELK4 in prostate cancer." (PMID 41155268, 2025). "It contains most of the promoter region of SLC45A3 and only the non-coding region of exon 1 and results in overexpression of FGFR2 in some patients with prostate cancer." (PMID 37370984, 2023). "One example is the well-studied cis-SAGe fusion between solute carrier family 45 member 3 (SLC45A3) and the ETS transcription factor ELK4 found in prostate cancer." (PMID 36527429, 2023). "Although ALK expression was uncommon in primary prostate cancers, we identified one case with high-level ALK protein expression due to a novel structural rearrangement involving SLC45A3 and ALK." (PMID 36337169, 2022). "GOLM1, CD24, PSCA, and the gene fusion TMPRSS2-ERG were selected as overexpressed mRNAs in prostate cancer, whereas ANXA3 and SLC45A3 were selected as underexpressed mRNAs in prostate cancer for evaluation." (PMID 33172003, 2020). "Transcriptome sequencing of these samples revealed a SLC45A3-SKIL fusion in LuCaP-77 and a MIPEP-SKIL fusion in the clinical sample, confirming SKIL as a recurrent 3′ fusion partner in prostate cancer." (PMID 25749039, 2015). "Recently, fusions involving SKIL (which encodes a SMAD inhibitor) 3′ to androgen-regulated promoters such as TMPRSS2, SLC45A3, and ACPP, were found in 6 of 540 (1.1 %) prostate cancers and one cell line xenograft, LuCaP-77." (PMID 26684754, 2015). "In addition, androgen and genotoxic stress recruit cytidine deaminase (AID) and LINE1-encoded ORF2 endonuclease to the specific sites and induce DNA cleavage of TMPRSS2, SLC45A3, ERG, and ETV1 in prostate cancer." (PMID 36579559, 2022). "SLC45A3 is mainly expressed in BRCA and KIRC, resulting in prostate cancer." (PMID 36016607, 2022). "The further RNA-seq expression of prostate related genes, PSCA and SLC45A3, are sufficient to deem ACRJ-PC28 a prostate-derived cell line, especially because NKX3.1 was the only prostate-specific biomarker detected in the Bob prostate cancer cell line." (PMID 36643868, 2022). "Amongst prostate cancer fusion genes, especially the effects of androgen-regulated SLC45A3-BRAF and a non-androgen-regulated ESRP1-RAF1 are targetable." (PMID 33634124, 2021). "Additional markers for primary prostatic cancers have been investigated, including prostate-specific membrane antigen (PSMA), prostate-specific acid phosphatase (PSAP), prostein (also known as p501s or SLC45A3), ETS-related gene (ERG), androgen receptor (AR)." (PMID 33450939, 2021). "These SLC45A3-ETS fusions and the fusions involving SKIL have not been reported in prostate cancer cell lines." (PMID 33634124, 2021). "For ETS fusion-negative prostate cancers subtypes, novel gene fusions have also been identified, including SLC45A3:BRAF, ESRP1:RAF1, SLC45A3:BRAF, ESRP1:RAF1, C15orf21:Myc, EPB41:BRAF, and TMEM79:SMG5." (PMID 23957008, 2013). "Even the combination of the five genes, including LARP4B, PLEKHF2, SMC4, SLC45A3 and NO6632,39,44,45,48,51, whose clinical relevance and prognostic implications were observed in prostate cancer, had very limited prediction strength for BCR and RFS (not reported in the Results section)." (PMID 35732666, 2022).
prostate carcinoma (continued). "In addition, transcriptome sequencing of ETS-fusion-negative prostate cancer revealed genetic rearrangements involving RAF-kinase family members, namely SLC45A3-BRAF and ESRP1-RAF1, recurrent in about 2% of advanced PCa cases, the former one being AR-regulated." (PMID 33634124, 2021).
prostate tumors (3 papers, 2011 to 2020). "Furthermore, 17 and 25 of the ERG positive prostate tumors, respectively, harbored SLC45A3 or PTEN expression loss." (PMID 29088771, 2017). "Loss of SLC45A3 and PTEN protein expression were detected in 30% and in 34% of prostate tumors, respectively, and similar to the previous literature, were statistically associated with higher GS." (PMID 29088771, 2017). "Regarding the ERG negative cases, single PTEN loss was found in 18, single SLC45A3 loss in 18, and the double PTEN/SLC45A3 loss in 10 prostate tumors." (PMID 29088771, 2017). "We found that the 5' gene SLC45A3 is expressed specifically in prostate tumor and normal samples, whereas the 3' gene ELK4 is expressed broadly across multiple tissues." (PMID 21261984, 2011). "In addition, the coexistence of TMPRSS2-ERG and SLC45A3-ERG rearrangements has been identified in a subset of prostate tumors." (PMID 29088771, 2017). "In order to analyze the impact of SLC45A3 and PTEN alterations on ERG pathway activation, prostate tumors were divided in 2 groups depending on ERG immunohistochemical expression being positive (n = 103) or negative (n = 117)." (PMID 29088771, 2017). "In order to validate our previous results, we have analyzed the immunohistochemical expression of ERG, SLC45A3 and PTEN in a large, independent cohort of prostate tumors collected in nine TMA blocks." (PMID 29088771, 2017). "In order to analyze the potential relationship of SLC45A3 and PTEN alterations with the ERG pathway activation, prostate tumors were divided in 2 groups according to the results of ERG IHC: ERG positive (n = 103) and ERG negative (n = 117)." (PMID 29088771, 2017). "Interestingly, in keeping with our previous study, the “triple hit” immunohistochemical phenotype (ERG positive/SLC45A3 loss/PTEN loss) was strongly associated with high grade prostate tumors, while this phenotype was completely absent among cases with GS = 6 or GG1." (PMID 29088771, 2017). "The Expression Atlas adds the observation that expression levels of TMPRSS2 and SLC45A3 vary across tissue and tumor types but that both TMPRSS2 and SLC45A3 are highly expressed in normal prostate tissues and prostate tumors, as shown in the Expression Atlas Baseline Expression Widget." (PMID 32636365, 2020).
adenocarcinoma of the prostate (2 papers, 2021 to 2025). "In descending order of importance for the prostate lineage genes, NKX3-1, KLK3, ACPP, SLC45A3 and FOLH1 were the most important predictors for prostate adenocarcinoma based on the discriminant loading > 0.3." (PMID 33762601, 2021). "Standard discriminant analysis of this study demonstrated that many of the prostate lineage markers genes were important predictors for prostate adenocarcinomas i.e. NKX3-1, KLK3, ACPP, SLC45A3 and FOLH1, corresponding to NKX3.1, PSA, PSAP, P501S, and PSMA respectively." (PMID 33762601, 2021).
breast carcinoma (2 papers, 2021). "Fusion partners of FGFR2 reported specifically in breast cancer are AFF3, CASP7 and CCDC6, while partners identified in other cancers include TACC and KIAA family members, PPHLN1, NTRK1, BICC1, AHCYL1, OFD1 and SLC45A3." (PMID 34344433, 2021).
epilepsy (1 paper, 2024). A brain disorder characterized by episodes of abnormally increased neuronal discharge resulting in transient episodes of sensory or motor neurological dysfunction, or psychic dysfunction. "The two remaining upregulated genes associated with the ACTG risk haplotype, RHEX and SLC45A3, do not have a clear connection to either epilepsy or the Wnt/β-catenin signaling pathway." (PMID 39596674, 2024).
kidney stone (1 paper, 2023). "Moreover, SLC45A3 and SLC26A9 were involved in the biological process of ion transport and pH regulation, which was crucial to kidney stone formation." (PMID 37980427, 2023).
melanoma (1 paper, 2024). A malignant, usually aggressive tumor composed of atypical, neoplastic melanocytes. "A genetic variant of SLC45A3 is associated with survival rate in melanoma and the function of the SLC45 gene family—mediating the transport of sugar molecules across the plasma membrane." (PMID 38849341, 2024).
Obesity (1 paper, 2020). Accumulation of substantial excess body fat. "The closest genes to the two novel loci, SLC45A3 and NEDDL4, have not been strongly linked to obesity in previous studies and databases, indicating that functional studies are needed to identify possible biological pathways." (PMID 33045005, 2020).
Sleep apnea (1 paper, 2017). An intermittent cessation of airflow at the mouth and nose during sleep is known as sleep apnea. "Suggestive associations of symptoms of sleep apnea were observed with 11 rare variants (located in KANK2, LCN6, TRAF3, PLEK, HIF1A, SLC45A3, ERCC1/CD3EAP, MRGPRE, GRAMD4, TYW5, CST5)." (PMID 29093733, 2017).
cancer (15 papers, 2014 to 2024). A tumor composed of atypical neoplastic, often pleomorphic cells that invade other tissues. "In addition to the proteins that can be causatively linked to cancer, there are others, such as solute carrier family 45 member 3 (UniProt accession Q96JT2) which are differentially expressed in cancer but not presently believed to be drivers of cancer." (PMID 25822509, 2015). "Enrichment analysis was performed using HUGO symbols of genes recurrently hit per dataset, indicating that the pathway “Transcriptional misregulation in cancer [KEGG:05202]” was significantly more frequently hit (P = 1.6 × 10−4) within PCa due to TMPRSS2, ERG, ETV1, H3FA3, SLC45A3, and ELK4." (PMID 34891161, 2021). "Cancer-related genes HDC, GATA2, and SLC45A3 were downregulated and S100A9 was upregulated by CUMS." (PMID 34650925, 2021). "In the cancer areas of samples 2.4 and 3.3 there are no spots with much higher expression of SLC45A3 than ELK4 (dark blue), hence no strong absence of the cis-SAGe is predicted in these areas." (PMID 32753032, 2020). "In addition, certain structural rearrangements were exclusively found in specific cancer types, as is the case for SLC45A3-BRAF and TMPRSS2-BRAF structural rearrangements in prostate tumors and no other cancer types." (PMID 39018217, 2024).
tumor (14 papers, 2014 to 2025). "The “triple hit” phenotype (ERG positive/SLC45A3 loss/PTEN loss) was statistically associated with tumor foci containing pattern 3 areas as well." (PMID 29088771, 2017). "We have reported that mRNA expression of TMPRSS2-ERG and SLC45A3-ERG rearrangements plus PTEN loss define an aggressive tumor subset." (PMID 29088771, 2017). "Our aim was to analyze the protein expression of PTEN, SPOP, SLC45A3, ETV1, ERG and the “triple hit” (ERG overexpression, PTEN plus SLC45A3 loss) in unifocal (UF) and MF PCa, to evaluate their value as prognostic markers according to focality, and the role of tumor heterogeneity in MF disease." (PMID 38017230, 2024). "For example, in comparison with normal samples, hypomethylation of SLC45A3 locus significantly correlates with most of the genes in PCa tumor samples, implying its role in PCa progression." (PMID 34051063, 2021). "TMPRSS2 and SLC45A3 rearrangements may coexist in the same tumor." (PMID 29088771, 2017). "The molecules that were differentially expressed in tumor and normal tissues by R software analysis were TMEM79, SMG5, NAA35, SLC45A3, FLG, TMEM254." (PMID 37936239, 2023). "SLC45A3-ERG, identified in 2/115 (1.7%) tumours from African patients, after TMPRSS2-ERG is the second most common fusion event in ERG positive PCa tumours, while SLC45A3-ETV1 fusion has also been reported." (PMID 36045381, 2022). "HDC, GATA2, SLC45A3, and NTRK1 were downregulated in tumor-bearing mice subjected to chronic unpredictable mild stress (CUMS)." (PMID 34650925, 2021). "Furthermore, double rearrangements of ERG with TMPRSS2 and SLC45A3 or NDRG1, well known androgen-induced genes, have been found to coexist in the same tumor in a subset of PrCa cases." (PMID 29088771, 2017). "The case 1 with the non-frameshift insertion of both MAGI1 and SLC45A3 was died 27 months after the operation because of metastases to the liver and bone, while the molecular mechanism of MAGI1 and SLC45A3 to the cervical grade 2 tumor of this case is sill unknown and need to further study." (PMID 31228945, 2019).
SLC45A3 also shares sentences with these, for which no sentence is quoted: brain injury (1 paper); glioblastoma (1); hemorrhage (1); metastatic disease (1); Parkinson disease (1); pulmonary hypertension (1).